PTPN22 (protein tyrosine phosphatase non-receptor type 22)
Diseases named in the same sentence as PTPN22 in open-access papers (continued):
Sharing a sentence is not in itself a finding about the gene and the disease.
autoimmune disease (continued). "Our results suggest a dual role of the PTPN22 polymorphism in the development of autoimmune diseases: while rs2476601 polymorphism was associated with increased risk for T1D, it was protective against development of CD." (PMID 30915320, 2019). "Numerous studies have confirmed this association, and implication of the PTPN22 1858 C/T polymorphism was also proposed in other autoimmune diseases." (PMID 30871019, 2019). "We synthesized all meta-analyses reporting a genetic association of the PTPN22 1858T C/T polymorphism with autoimmune diseases." (PMID 30871019, 2019). "Our results suggest opposite effects of PTPN22 variant on T1D and CD susceptibility and provide interesting information on incidence of this variant in subjects diagnosed with both autoimmune diseases together." (PMID 30915320, 2019). "Our finding that PTPN22 polymorphism has a dual role in the development of autoimmune diseases is of particular interest as recent studies showed that NLRP3 activation is negatively regulated by tyrosine phosphorylation." (PMID 30915320, 2019). "Many single nucleotide polymorphisms (SNPs) have been identified in PTPN22, but only one non-synonymous SNP has been intensively studied in relation to autoimmune diseases." (PMID 30871019, 2019). "PTPN22 has been identified as the main susceptible gene for multiple autoimmune diseases, including rheumatoid arthritis, juvenile idiopathic arthritis, psoriatic arthritis, systemic lupus erythematosus, systemic sclerosis and some forms of vasculitis." (PMID 30384852, 2018). "It has been linked with multiple inflammatory disorders and in fact, PTPN22 genetic variation is among the strongest genetic risk factors for autoimmunity diseases such as type I diabetes (T1D), rheumatoid arthritis and systemic lupus erythematosus." (PMID 30429852, 2018). "HLA-DRB1 and PTPN22 are genes involved in the immune response, which have been commonly associated with HT and other autoimmune disorders in the literature." (PMID 29931474, 2018). "In contrast, a common gain-of-function polymorphism of PTPN22 has been found in humans that is associated with increased risk in homozygous individuals of developing a wide range of autoimmune diseases." (PMID 30271775, 2018). "It is important to note that a PTPN22 deficiency can cooperate with the E613R CD45 mutant to induce autoimmune diseases." (PMID 30429852, 2018). "A C1858T single nucleotide polymorphism within PTPN22 (which encodes PTPN22R620W) is associated with an enhanced susceptibility to multiple autoimmune diseases including type 1 diabetes and rheumatoid arthritis." (PMID 30139951, 2018). "Although the association of Ptpn22 genetic variants with autoimmune disease has been proposed to be due to its role in lymphocyte signaling, environmental factors are also critical to the initiation of autoimmune arthritis." (PMID 28948613, 2018). "We show that CD8+ T cells that lack the tyrosine phosphatase Ptpn22, a major predisposing gene for autoimmune disease, are resistant to the suppressive effects of TGFβ." (PMID 29116089, 2017). "Single-nucleotide polymorphism (SNP) rs2476601 within protein tyrosine phosphatase non-receptor type 22 gene (PTPN22) has been shown to be a risk factor for different autoimmune diseases." (PMID 27215233, 2017). "A single nucleotide polymorphism in the PTPN22 gene (rs2476601) imparts altered risk for infection and autoimmune disease." (PMID 28723925, 2017). "PTPN22 C1858T belongs to a growing family of shared autoimmunity loci, which are associated with various autoimmune disorders." (PMID 27215233, 2017). "Two polymorphic variants (−1123G>C and +1858C>T) at PTPN22 gene that encodes this protein have been associated with autoimmune disorders and found in strong linkage disequilibrium in Caucasian population." (PMID 28210620, 2017).
autoimmune disease (continued). "The results of our study open the pathway to future trials for the treatment of autoimmune diseases based on the selective inhibition of variant PTPN22 allele using lipoplexes of siRNA antisense oligomers." (PMID 28437437, 2017). "A coding polymorphism (R620W) in PTPN22 imparts elevated risk for human infection and autoimmune disease, predisposes to diminished innate immune responses, and associates with reduced immunization responses." (PMID 28723925, 2017). "Recent genome-wide association analysis has identified a single-nucleotide polymorphism, R620W, in the PTPN22 gene as a predominant risk factor for RA and other autoimmune diseases (reviewed in Ref." (PMID 27288531, 2016). "A missense single nucleotide polymorphism (SNP) (rs2476601) in PTPN22 has been linked to numerous autoimmune diseases in Caucasians." (PMID 27406031, 2016). "In recent studies on the PTPN22 gene, the rs2476601 missense substitution SNP has been associated with multiple autoimmune diseases in Caucasians, including RA, SLE, Graves’ disease, and Addison’s disease." (PMID 27406031, 2016). "PTPN22 620W allele plays a role in autoimmune disorders, and underscores the importance of a genetically mediated autoimmune mechanism in the pathogenesis of vitiligo." (PMID 26870082, 2016). "Variants of PTPN22 also are associated with a number of different autoimmune diseases, including RA and SLE." (PMID 26870082, 2016). "A missense SNP in PTPN22 (PTPN22-C1858T) predisposes carriers to a number of autoimmune diseases, most notably RA, systemic lupus erythematosus, and type 1 diabetes." (PMID 27807193, 2016). "Meanwhile, several studies have implicated PTPN22 SNPs with autoimmune disorders independently of rs2488457, suggesting that such polymorphisms play a general role in autoimmunity." (PMID 27406031, 2016). "Of note, polymorphisms in PTPN22 that render B-cells (and T and innate cells) hyper-responsive and are associated with many autoimmune diseases." (PMID 25717326, 2015). "The non-receptor tyrosine phosphatase PTPN22 has a vital function in inhibiting antigen-receptor signaling in T cells, while polymorphisms in the PTPN22 gene are important risk alleles in human autoimmune diseases." (PMID 25715232, 2015). "In conclusion we report for the first time genome-wide significant association of the rs2476601 variant in the PTPN22 gene with susceptibility to PsA consistent with reports in many other autoimmune diseases." (PMID 25923216, 2015). "PTPN22 also represented a strong susceptibility gene, which was shared by many autoimmune diseases such as T1D, psoriasis, and SLE." (PMID 26253105, 2015). "The human ortholog of Ptpn22, PTPN22, is associated with numerous autoimmune diseases, including T1D." (PMID 26438525, 2015). "Taken together, the results in terms of PTPN22/CSK association with autoimmune diseases support the notion that different pathogenic mechanisms are involved in the development of polygenic disorders." (PMID 26458874, 2015). "In humans, the PTPN22 variant associated with susceptibility to autoimmune disease is a nonsynonymous SNP, R620W, in exon 14, which encodes a proline-rich region that interacts with C-terminal Src kinase." (PMID 26438525, 2015). "Genome-wide association studies have identified a missense single nucleotide polymorphism of Ptpn22 that is strongly associated with higher risk of several autoimmune diseases, including rheumatoid arthritis and SLE." (PMID 25993510, 2015). "Although similar associations of PTPN22 rs2488457 SNP have been found in many other autoimmune diseases, few studies are available regarding the role of rs2488457 SNP in the genetic susceptibility to JIA." (PMID 25781893, 2015). "Ptpn22 is the most striking candidate, as the human ortholog, PTPN22, is associated with several autoimmune diseases." (PMID 26438525, 2015).
autoimmune disease (continued). "Variations in PTPN22, and specifically R620W, are associated with various autoimmune disorders including type 1 diabetes, rheumatoid arthritis, systemic lupus erythematosus and Graves' disease." (PMID 24586183, 2014). "The PTPN22 R620W polymorphism is accepted as a general risk factor for autoimmune diseases with prominent production of auto-antibodies." (PMID 25119822, 2014). "For several autoimmune diseases characterized by specific autoantibodies like rheumatoid arthritis, type 1 diabetes and systemic lupus erythematosus, a significant association with PTPN22 gene polymorphisms has been demonstrated by several groups." (PMID 24816862, 2014). "MG was shown to be associated with PTPN22 R620W polymorphism similar to several other autoimmune diseases." (PMID 25119822, 2014). "In contrast to findings in other autoimmune diseases, the distribution of the PTPN22 polymorphism in this population provides a susceptibility marker for AChR-MG." (PMID 25119822, 2014). "One of the most common genetic associations with autoimmune disorders is the protein tyrosine phosphatase gene PTPN22 expressed in lymphocytes." (PMID 24900918, 2014). "PTPN22 appears to be the second most important genetic risk factor for autoimmune diseases, following the HLA system." (PMID 24985973, 2014). "A critical clue is provided by the PTPN22 rs6679677 C/A polymorphism that is in high linkage disequilibrium with the rs2476601 C/T polymorphism associated with many autoimmune diseases." (PMID 24988487, 2014). "A functional single nucleotide polymorphism (SNP) of the PTPN22 gene encoding a protein tyrosine phosphatase has been associated with autoimmune disorders including myasthenia gravis (MG)." (PMID 25119822, 2014). "Association of certain autoimmune disorders and T1858 allele of the PTPN22 gene has been confirmed in many populations, although the T1858 allele frequencies vary considerably in different ethnic groups." (PMID 24985973, 2014). "The tryptophan allele within PTPN22 has been found in patients with many autoimmune disorders, including type 1 diabetes mellitus, rheumatoid arthritis (RA), systemic lupus erythematosus (SLE), and autoimmune thyroiditis." (PMID 24900918, 2014). "The R620W (C1858T, rs2476601) polymorphism in PTPN22 exon 14 was first associated with type 1 diabetes and subsequently with other autoimmune disorders such as rheumatoid arthritis, systemic lupus erythematosus, and systemic sclerosis." (PMID 23559857, 2013). "Protein tyrosine phosphatase non-receptor type 22 (PTPN22) is a negative regulator of T-cell activation associated with several autoimmune diseases, including systemic lupus erythematosus (SLE)." (PMID 23950893, 2013). "Two independent functional missense single nucleotide polymorphisms (SNPs) located within the PTPN22 gene (R263Q and R620W) have been associated with different autoimmune disorders." (PMID 23559857, 2013). "Two are non-synonymous variants in genes associated with many autoimmune diseases (PTPN22 R620W and SH2B3 (SH2B adaptor protein 3) R262W) and a third is in the HLA class I region." (PMID 22493691, 2012). "An association with the PTPN22 T allele, which has been described in other autoimmune diseases, has been reported in bilateral MD; these data support the idea of an inflammatory mechanism common to different autoimmune diseases." (PMID 22315686, 2012). "Apart from polymorphisms within the major histocompatibility complex (MHC) and CTLA-4, a 1858 T>C polymorphism of PTPN22 gene is currently a recognized risk factor for autoimmune diseases." (PMID 23072316, 2012). "In this study the +1858T allele of the PTPN22 gene, known to be associated with several autoimmune diseases, was associated with PsA." (PMID 21410964, 2011). "The PTPN22 gene is shown in numerous studies to be associated with the development of type 1 diabetes and other autoimmune diseases." (PMID 21429197, 2011).
autoimmune disease (continued). "In a number of studies, the non-synonymous variant, C1858T, of the PTPN22 gene has been associated with development of type 1 diabetes as well as other autoimmune diseases." (PMID 21429197, 2011). "The best documented association of PTPN22 variants to autoimmune disorders including GD is rs2476601 (C1858T)." (PMID 22654555, 2011). "Similar heterogeneity between autoimmune diseases has also been observed in PTPN22, where the 1858T allele is associated with predisposition in T1D, GD, HT and RA, but confers protection in Crohn’s disease (CD)." (PMID 22654554, 2011). "Rare variants in a number of genes, e.g. PTPN22, have been shown to be associated with autoimmune diseases such as AD and diabetes." (PMID 21851588, 2011). "In this study of clinically and laboratory well characterized patients with PsA, the +1858T allele of the PTPN22 gene, previously shown to be associated with several autoimmune diseases, was found to be associated with a diagnosis of PsA." (PMID 21410964, 2011). "1858C/T SNP of the PTPN22 gene, resulting in arginine to tryptophan substitution at codon 620 (R620W), was demonstrated to be a risk factor for many autoimmune diseases." (PMID 22654557, 2011). "The Trp620 allotype of PTPN22 confers susceptibility to rheumatoid arthritis (RA) and certain other classical autoimmune diseases." (PMID 20975833, 2010). "PTPRM is a receptor-type protein tyrosine phosphatase, which is of particular interest as a number of protein tyrosine phosphatases have been linked to autoimmune disease, including PTPN22 and PTPN2." (PMID 20659327, 2010). "For example, a number of autoimmune diseases have been associated with variants in the PTPN22, TNFAIP3 and CTLA4 genes." (PMID 20854658, 2010). "The association of IL2RA/CD25 with a fifth autoimmune disease suggests that this gene, along with the PTPN22 gene, appears to play a vital role in immune regulation and function as well as predisposition to autoimmunity in general." (PMID 19116909, 2009). "An SNP of PTPN22, R620W (rs2476601) was reported to be associated with several autoimmune diseases such as RA, SLE, and IDDM." (PMID 19503742, 2009). "A functional single nucleotide polymorphism (SNP) of the gene encoding protein tyrosine phosphatase type 22 (PTPN22; R620W rs2476601, 1858C/T) has recently been described as a strong common genetic risk factor for human autoimmune disease." (PMID 19180256, 2009). "Across different autoimmune diseases some genes with immunomodulatory roles, such as PTPN22, are frequently associated with multiple diseases, whereas specific HLA associations, such as HLA-B27, tend to be disease restricted." (PMID 19951419, 2009). "In man, the C1858T (R620W) allelic variant of Ptpn22 has been linked to multiple human autoimmune disorders that have a prominent humoral component, including SLE, rheumatoid arthritis, type 1 diabetes, and autoimmune thyroiditis." (PMID 19578517, 2008). "The role of Ptpn22/Ptpn8 as a susceptibility gene in mouse autoimmune diseases is less well characterized, although gene variants have been linked to type 1 diabetes in NOD mice." (PMID 19578517, 2008). "The PTPN22 +1858T allele has been associated with susceptibility to autoimmune diseases including systemic lupus erythematosus, type 1 diabetes mellitus, Graves' disease, and RA." (PMID 17665434, 2007). "Several of the autoimmune diseases associated with the PTPN22 1858T variant are characterized by the presence of autoantibodies." (PMID 17553139, 2007). "The minor allele of R620W (rs2476601) is a missense SNP in the hematopoietic-specific protein tyrosine phosphatase gene, PTPN22, and has been associated with multiple autoimmune diseases, including RA." (PMID 18466572, 2007). "The PTPN22 polymorphism is associated with several other autoimmune diseases, while HLA-SE is strongly related only to RA." (PMID 17553139, 2007).
autoimmune disease (continued). "The PTPN22 1858C/T polymorphism has been associated with several autoimmune diseases including rheumatoid arthritis (RA)." (PMID 17553139, 2007). "The association of several autoimmune diseases with the PTPN22 1858C/T SNP has been considered as indicative of the existence of an inflammatory process common to many autoimmune diseases." (PMID 16539704, 2006). "In the first study showing association of the variant PTPN22 SNP with autoimmune disease, a gene dosage effect has been suggested, since individuals homozygous for the PTPN22 1858T allele were most likely to develop type I diabetes." (PMID 16635271, 2006). "The PTPN22 1858C/T polymorphism was originally associated with type I diabetes and later with other autoimmune diseases, for example, systemic lupus erythematosus, Graves' disease and Hashimoto thyroiditis." (PMID 16507117, 2006). "The 1858C/T SNP of the PTPN22 gene has been associated with many autoimmune diseases, suggesting the existence of an inflammatory process common to all of them." (PMID 16539704, 2006). "PTPN22 has been found associated with most autoimmune diseases studied so far, specifically with some of the most prevalent ones, Graves disease, rheumatoid arthritis, systemic lupus erythematosus and type 1 diabetes." (PMID 16539704, 2006). "This is the first study to show an association between the PTPN22 1858T variant and a disease related autoantibody, and that they co-operate to increase the relative risk of developing an autoimmune disease, in this case RA." (PMID 16507117, 2006). "Recently, a single-nucleotide polymorphism (SNP) of the PTPN22 (protein tyrosine phosphatase, non-receptor type 22) gene, 1858C/T, has been found associated with many autoimmune diseases." (PMID 16539704, 2006). "An association has recently been reported between the PTPN22-620W functional allele and rheumatoid factor-positive (RF+) rheumatoid arthritis (RA), among other autoimmune diseases." (PMID 16277672, 2005). "It will consequently be of major interest to test further for association of the PTPN22-1858T allele in RA families with a clustering of multiple autoimmune diseases to measure precisely this association with each disease." (PMID 16277672, 2005). "Notably, variations in the PTPN22 gene, particularly the R620W polymorphism, have been linked to an increased risk of autoimmune disorders, including T1D." (PMID 40238817, 2025). "Among these, particular attention is paid to the potential pathophysiological role played in autoimmune disorders, including T1D and APS3v, by the C1858T variant of the PTPN22 (protein tyrosine phosphatase N22) gene, which encodes for the R620W variant Lyp protein tyrosine phosphatase." (PMID 40574023, 2025). "Similarly, PTPN22 is closely linked to autoimmune diseases like SLE and is known to negatively regulate T-cell activation." (PMID 40321894, 2025). "Notably, a C1858T SNP, corresponding to an arginine (R) to tryptophan (W) mutation at position 620 in the P1 proline-rich motif of PTPN22 leads to reduced binding to C-terminal Src Kinase and increased risk of several autoimmune diseases." (PMID 38777143, 2024). "PTPN22 is implicated in various autoimmune diseases, including cancer." (PMID 39451542, 2024). "We summarize recent progress in our understanding of the regulation of PTPN22 activity, the impact of autoimmune disease-associated PTPN22 SNPs on T cell responses and describe approaches to harness PTPN22 as a target to improve T cell-based immunotherapies in cancer." (PMID 39039893, 2024). "This would help explain how PTPN22 could influence risk of diverse autoimmune diseases such as type 1 diabetes and rheumatoid arthritis, diseases with distinct ages of onset and tissue targets." (PMID 36961507, 2023).